S100B (S100 calcium binding protein B)
Diseases named in the same sentence as S100B in open-access papers (continued):
Sharing a sentence is not in itself a finding about the gene and the disease.
neurological diseases (65 papers, 2010 to 2026). "In many neurological diseases, S100B is often considered to be a damage-associated molecular pattern (DAMPs) indicator and emergency valve." (PMID 39908332, 2025). "We did not observe any evidence for reverse causality of these neuropsychiatric or neurological disorders on altered S100B levels." (PMID 37225692, 2023). "Here, we present the first study investigating the causal effect of circulating S100B levels on the risk of six major neuropsychiatric or neurological disorders." (PMID 37225692, 2023). "S100B is expressed mainly in astrocytes and other glial cells, and S100B has been reported to be associated with various neurological disorders." (PMID 36766438, 2023). "Circulating levels of the astrocytic marker S100B have been associated with risk of neuropsychiatric or neurological disorders." (PMID 37225692, 2023). "The presented bioinformatic analysis of the human diseases associated with simultaneous involvement of IFN-β and S100B shows that the IFN-β–S100B interaction is also relevant to pathogenesis of numerous neurological diseases." (PMID 35216109, 2022). "S100B expression is highest in the brain, and high levels of S100B are associated with neurodegeneration and other neurologic disorders." (PMID 34360919, 2021). "We have characterised the genetic and epigenetic profiles of S100β, a circulating protein that has been associated with brain inflammation and neurological disease pathology." (PMID 35028426, 2021). "S100B is regarded to be associated with several diseases and neurological disorders where the microbiota also seems to play a role (for reviews,)." (PMID 32679810, 2020). "Pharmacological inhibition of S100B synthesis mitigates hallmark pathologies of both brain diseases, opening the door for translational approaches to treat these devastating neurological disorders." (PMID 20862385, 2010). "S100B has been implicated in several neurological disorders including TBI, AD, PD, ALS, and MS." (PMID 36268187, 2022). "In addition, we observed that in individuals carrying rs1051169CC genotype there was an association with abnormal expression of S100B in SLEpatients with neurologic disorder." (PMID 31271591, 2019). "Nevertheless, more than S100B depletion, elevated levels of S100B may occur under physiological and pathological conditions within the brain and have been implicated in several neurological disorders." (PMID 29386995, 2017). "Importantly, we propose that both of these neurological diseases share a common pathogenic mechanism—maladaptive astrocytic activation—where S100B acts as a perpetrator of neuroinflammation and neurotoxicity." (PMID 20862385, 2010). "Therefore, using SNP instruments will suffer less from unknown environmental confounding on the causal relations between S100B and neuropsychiatric or neurological disorders." (PMID 37225692, 2023). "S-100β is an inhibitory soluble acidic calcium-binding protein present in nervous tissue, with low levels in serum and cerebrospinal fluid in non-neurological disorders." (PMID 40951886, 2025). "Here, we provide an overview of the structure and role of S100β in various pathways, particularly in the context of neurological disorders." (PMID 40843691, 2025). "Results also demonstrated that proinflammatory molecules such as S100B, IL-17, IL-33, and neurological disease signaling pathways were upregulated, while protective pathways like aryl hydrocarbon receptor signaling were downregulated." (PMID 38719902, 2024). "In many neurological disorders, S100B levels correlate with clinical or toxic parameters; thus, S100B can serve as a therapeutic target for neurological diseases." (PMID 37627641, 2023). "To date, most of the research on the clinical use of S100B has been conducted in patients with neurologic disorders or some malignancies." (PMID 36766438, 2023).
neurological diseases (continued). "Neurochemical studies have confirmed that some specific proteins, S100B protein and Aβ protein, can be used as markers in the diagnosis of some neurological diseases." (PMID 37713081, 2023). "S100B levels in peripheral blood have been suggested as a biomarker for neuropsychiatric and neurological disorders." (PMID 37225692, 2023). "Here we show that IFN-β interacts with one more representative of the S100 protein family, the S100B protein, involved in numerous oncological and neurological diseases." (PMID 35216109, 2022). "S100B is an established biomarker for tissue damage, aging, and neurological diseases, including AD." (PMID 35337097, 2022). "The cerebral biomarkers S100B, neuron specific enolase, (NSE), tau protein and neurofilament light chain (NfL) have proven useful as predictors and diagnostic tools in other neurological disorders." (PMID 33556141, 2021). "S100B is a Ca+2 binding protein mainly expressed by astrocytes and is used to detect glial activation or death in neurological disorders, or both." (PMID 34836309, 2021). "In this sense, S100β levels have been proposed as a biomarker of neurological disorders, and it has been observed that the levels of S100β in serum increased in patients who experienced unfavorable seizure outcomes." (PMID 32521797, 2020). "We found that the serum S100B levels in SLE patients with neurologicdisorder were significantly higher than in non-neurologic disorder patients andcontrols (p < 0.05, respectively)." (PMID 31271591, 2019). "S100B has been considered as a surrogate marker for astrocyte-specific damage in neurologic disorders." (PMID 27610173, 2016). "Measurements of S100B in serum have been proven to valuably reflect the S100B concentration in cerebrospinal fluid (CSF) in healthy individuals as well as in patients with various neurological diseases." (PMID 27013967, 2016). "S100B has been considered as a surrogate marker for brain and astrocyte-specific damage or dysfunction in neurologic disorders such as stroke and traumatic brain injury." (PMID 27610173, 2016). "A longitudinal link and a cause-effect relationship between BBBD and neurological diseases were made possible by use of peripheral markers of BBB dysfunction, such as the appearance in serum of the astrocytic protein S100B." (PMID 23483891, 2013). "Experiments are underway to determine if pharmacological inhibition of S100B expression and/or interaction of S100B with its target proteins will improve cognitive function in AD and/or other neurological disorders." (PMID 21080947, 2010). "Since our study was planned there has been an accumulation of data regarding the potential importance of inflammation and S100B concentrations in subjects with acute ischaemic stroke and other neurologic disorders." (PMID 21034449, 2010). "The insights from its role in other neurological disorders suggest that S100B may influence the outcomes of shunt surgery through its modulation of neuroinflammation, oxidative stress, and astrocyte activation." (PMID 40457021, 2025). "Additionally, the S100β protein is mainly found in astrocytes and is used as a marker in neurological diseases." (PMID 38601797, 2024). "It was shown that in the group of healthy individuals, CS100B ≥ 7.8 pg/mL was detectable in only 2% of participants, which may result from emerging neurological disorders, especially in one of two individuals with very high S100B levels (11,270 pg/mL)." (PMID 39519343, 2024). "Thus, when large samples become available, the effect of S100B on neuropsychiatric or neurological disorders will become clearer for this age group." (PMID 37225692, 2023). "Surprisingly, we did not observe any causal effect of S100B on four of the neuropsychiatric or neurological disorders studied." (PMID 37225692, 2023).
neurological diseases (continued). "Bioinformatics analysis showed that the direct modulation of IFN-β activity by the S100B protein described here could be relevant to progression of multiple oncological and neurological diseases." (PMID 35216109, 2022). "Previous comparative transcriptomics of the visual cortex have revealed that S100B and clusterin (apolipoprotein J), two stress proteins that are involved in neurological disorders characterized by hypoxic conditions, have a remarkably high expression in hooded seals compared to ferrets." (PMID 36243678, 2022). "This context may aid in understanding the role of S100β in brain inflammation and neurological disease." (PMID 35028426, 2021). "In addition, SLE patientswith neurologic disorder carrying the rs1051169 GC/CC genotypes present a higherserum S100B levels compared with that carrying the GG genotype(p < 0.05)." (PMID 31271591, 2019). "From the other side, it has been shown that extracranial sources of S100B do not affect serum levels and protein's diagnostic value in neurological diseases in intact subjects." (PMID 26417594, 2015). "It has since been postulated that S100B may act as an inflammatory mediator in subjects with non-neurologic disease." (PMID 21034449, 2010). "We also want to underscore that S100B is not a diagnostic tool for any particular neurological disease but rather an adjunctive means to predict evolution of disease or rule out the presence of underlying brain or cerebrovascular damage." (PMID 20559426, 2010). "Therefore, the diagnostic value of S100B and its negative predictive value in neurological diseases appear not to be compromised in the clinical setting." (PMID 36983411, 2023). "Wehypothesized that the synonymous SNP rs1051169 located in the exon of S100B mayexert an influence on splicing, thereby affecting the levels of serum S100B, whichultimately potentiate S100B-mediated pro-inflammatory processes, increase SLE risk,and promote neurologic disorder development." (PMID 31271591, 2019). "This could be because S100B is a sensitive marker of sub-clinical neurologic disease." (PMID 21034449, 2010). "Thus, the diagnostic value of S100B and its negative predictive value in neurological diseases in intact subjects (without traumatic brain or bodily injury from accident or surgery) are not compromised in the clinical setting." (PMID 20844757, 2010). "Finally, the beneficial effects of S100B ablation/inhibition may extend to other neurological disorders that involve dysregulation of glial cell calcium homeostasis." (PMID 21080947, 2010). "A broad range of neurological disorders increase cerebrospinal fluid and serum levels of neuron-specific enolase (NSE) and S-100b protein." (PMID 39199513, 2024). "For example, levels of the brain-derived glial fibrillary acidic protein (GFAP), S100B, tau and Ubiquitin C-Terminal Hydrolase L1 (UCHL-1) in biological fluids have been shown to correlate with presence and severity of many neurological disorders." (PMID 27903281, 2016). "The positive predictive value of S100B is poor, since levels above threshold indicate BBBD which is a feature of many neurological diseases." (PMID 23483891, 2013). "Lastly, a common motif in S100B diagnostics is that S100B is not specific for any neurological disease." (PMID 35546671, 2022). "We have established evidence for modest genetic, but not epigenetic contributions to the levels of S100β, a protein marker for brain inflammation and neurological disease." (PMID 35028426, 2021). "S100B, NSE, tau and NfL have been evaluated in other neurological disorders before." (PMID 33556141, 2021). "Our results also reiterate that S100B has no predictive value for any particular neurological disease, since elevated levels are present when the BBB is breached or when severe brain damage occurs." (PMID 20559426, 2010).
neurodegenerative disease (56 papers, 2010 to 2026). A disorder of the central nervous system characterized by gradual and progressive loss of neural tissue and neurologic function. "Activation of astrocytes with an increased expression of GFAP and S100β is a hallmark of brain diseases, including common late-onset neurodegenerative diseases, ischemic brain injuries, and epilepsy." (PMID 33441619, 2021). "The alarmins and signaling pathways more frequently associated with the neurodegenerative diseases comprise β-amyloid, α-synuclein, defensins, exogenous S100B, HMGB1, Hsp, and IL-33." (PMID 33114371, 2020). "The use of oxytocin as a therapeutic agent, administered intranasally or through other delivery methods, could be explored as a strategy to mitigate S100B overexpression in aging populations and individuals at risk for neurodegenerative diseases." (PMID 40487975, 2025). "However, S100β at micromolar concentrations acts as a cytokine or damage-associated molecular pattern protein, playing a major role in neurodegenerative diseases associated with dysregulated glial cell proliferation and neuroinflammation." (PMID 41153683, 2025). "Given its association with S100B, which is involved in neuroinflammatory responses, oxytocin‐based therapeutic strategies could be explored for neurodegenerative diseases." (PMID 40487975, 2025). "Several protein groups associated with aging and neurodegenerative diseases including apolipoprotein E (ApoE), S100B, Sod1, Sod2, huntingtin (Htt), macrophage migration inhibitory factor (Mif), α-Synuclein (Snca) were modulated by either drug treatment or the behavioural training per se." (PMID 34907284, 2021). "At nanomolar concentrations, S100B conveys neuroprotective and neurotrophic properties, while at higher concentrations it has been associated with deleterious effects, and may form the basis of neurodegenerative diseases such as Alzheimer’s Disease (AD)." (PMID 36076994, 2022). "CSF GFAP and S100B, as the markers of astrocyte activation, are significantly elevated in neurodegenerative diseases and contribute to neuroinflammation." (PMID 40702763, 2025). "It has been shown that in neurodegenerative diseases and other conditions leading to neuronal cell death, the level of S100β protein increases in astrocytes, extracellular space and in serum." (PMID 39767670, 2024). "S100B is an astrocytic cytokine that has been shown to be involved in several neurodegenerative diseases." (PMID 36982288, 2023). "The expression of HMGB1 and S100B was increased in neuron and glial cells in many neurodegenerative diseases, leading to excessive release of them and activation of RAGEs." (PMID 37433768, 2023). "Colocalization of S100β and the complement protein C3 is a marker for a subset of reactive neurotoxic astrocytes in a variety of neurodegenerative diseases." (PMID 37250395, 2023). "S100B is increased in several neurodegenerative diseases, where it has been postulated to be induced by microglial cytokines and to cause both intracellular and extracellular effects that lead to neurotoxicity." (PMID 37187609, 2023). "While the roles of CLU and S100B in neurodegenerative diseases are being debated, we found evidence for the upregulation of neuroprotective effects in cell lines overexpressing these genes, in response to hypoxia and oxidative stress." (PMID 36243678, 2022). "Transgenic mouse models overexpressing S100B have initially been developed to study its degenerative effects, and supported the idea of S100B as a marker of brain damage and neurodegenerative diseases." (PMID 36076994, 2022). "In neuronal disorders such as acute brain injury and neurodegenerative diseases, S100B has been found at high levels serving as a biomarker of disease progression." (PMID 36243678, 2022). "Elevated S100B levels accurately reflect the presence of neuropathological conditions including traumatic head injury or neurodegenerative diseases." (PMID 30468006, 2018).
neurodegenerative disease (continued). "Since augmented astrocytic S100B synthesis accompanies a diverse number of brain pathologies, we moved on to consider the role(s) of this enigmatic molecule in neurodegenerative disease." (PMID 20862385, 2010). "As we have seen, S100β is upregulated in neurodegenerative diseases and CNS injuries." (PMID 40843691, 2025). "We couldn’t find reports on the role of CSF S100B in treatment evaluation in patients with neurodegenerative diseases." (PMID 37474905, 2023). "Elevated levels of S-100β and Calpain were reported in neurodegenerative diseases." (PMID 35526035, 2022). "However, elevated S100β levels at other points in life mostly correlate with blood–brain barrier injury, which has been observed in cerebrovascular and neurodegenerative diseases." (PMID 35982410, 2022). "Overexpression of S100B in the mice brain is known to accelerate neurodegenerative disease pathology, including AD and PD, and promote the synthesis of APP mRNA and APP in neurons, which could serve as a source of additional Aβ accumulation." (PMID 24586443, 2014). "The availability of selective S100B biosynthesis inhibitors such as arundic acid is expected to further translational research for neurological and neurodegenerative diseases, and perhaps other disorders, such as inflammatory bowl disease, which are S100B overexpresssion-related." (PMID 20862385, 2010). "Finally, we consider the concept of translating S100B inhibition to the clinic for the treatment of neurodegenerative diseases." (PMID 20862385, 2010). "The significance of cerebral GFAP and S100B levels should be discussed according to the context; here, considering situations involved with brain damage, all of the compounds tested showed a similar profile, suggesting astrocytic dysfunction, as found in neurodegenerative diseases." (PMID 38535311, 2024). "Elevated S100B protein levels accurately reflect the presence of neuropathological conditions, including traumatic head injuries, psychiatric disorders, cerebrovascular insults and neurodegenerative diseases, whereas normal levels reliably exclude major CNS pathology." (PMID 22420334, 2012). "Astrocyte activation, marked by the overexpression of GFAP and S100β, can mediate inflammation and contribute to BBB disruption in neurodegenerative diseases (e.g., AD)." (PMID 41221374, 2025). "With this study, we illustrate a clear dysregulation and a possible proinflammatory role for the S100B-RAGE pathway in ALS, another neurodegenerative disease characterized by a strong neuroinflammatory component." (PMID 28713206, 2017). "A dysregulation of the S100B-RAGE system and its implication with pathological events have been observed in several neurodegenerative diseases, as Parkinson's (PD) and Alzheimer's (AD)." (PMID 28713206, 2017). "S100B is a multifunctional protein that, like GFAP, is relatively restricted to astrocytes and has served as a marker for brain damage in neurodegenerative diseases." (PMID 25166759, 2014). "Under pathological conditions, for example, neurodegenerative diseases, astrocyte activation, as reflected by increased GFAP and S100β levels, could lead to increased production of inflammatory mediators associated with BBB disruption." (PMID 41221374, 2025). "This may be true when S100B levels are in a physiological range, as is the case in MDD patients, or during early stages of neurodegenerative diseases." (PMID 26364276, 2015).